AR (androgen receptor)
Diseases named in the same sentence as AR in open-access papers (continued):
Sharing a sentence is not in itself a finding about the gene and the disease.
prostate tumors (continued). "Hypoxia has been associated with prostate tumor progression as it can allow for the selection of cells, which are androgen receptor(AR)-negative with abrogated apoptotic potential and a more invasive phenotype and being implicated in the epithelial to mesenchymal transition." (PMID 33917751, 2021). "As a non-steroid drug, the bicalutamide tablets used in this study have better peripheral selectivity and can bind to the androgen receptor without effective gene expression, thus inhibiting the stimulation of androgens and causing the atrophy of prostate tumors." (PMID 34795779, 2021). "However, the N-Myc overexpressed prostate tumors are resistant to AR-targeted therapies, including ADT and Enzalutamide, indicating that N-Myc re-establishes other AR-independent pro-survival mechanisms/pathways to drive the disease progression and therapeutic resistance development." (PMID 30657058, 2019). "Besides AR alterations, the overexpression of enzymes responsible for androgen synthesis and metabolism has been also proposed to explain the persistence of hormone-mediating signaling in prostate tumor cells under hormone deprivation state." (PMID 28903376, 2017). "However, in the PC346 model derived from a primary human prostate tumour subcutaneously implanted into athymic mice that were subsequently castrated, an androgen-independent subline, PC346DCC emerged that contained the K311R AR mutation." (PMID 27903893, 2017). "Therefore, N-AR cells were transfected with the androgen-responsive rat probasin luciferase reporter and treated with androgens to determine whether SBP-AR could mediate luciferase reporter expression similar to that of AR-T877A in LNCaP prostate tumor cells." (PMID 27365400, 2016). "Similarly, the enrichment of cytoplasmic ribosomal proteins in the AS sample is corroborated by the finding that androgens acutely (i.e. within hours) stimulate ribosomal RNA synthesis and ribosome biogenesis through an AR-dependent mechanism in prostate tumor cells." (PMID 27365400, 2016). "Thus, AR is required for Src activation in several different prostate tumor cell lines." (PMID 25730905, 2015). "One potential explanation for this finding is that liganded AR can negatively regulate its own expression: thus, the loss of AR protein associated with HSP90 inhibition, which occurs in AUY922-treated, ex vivo cultured prostate tumors, could de-repress the AR gene." (PMID 23674566, 2013). "Finally, Wnt-11 and AR were found to be co-expressed in prostate tumour cells." (PMID 20219091, 2010). "However, we have recently shown that cyclin D1b is upregulated in human prostate tumours, is selectively compromised for AR regulation, and may yield a specific growth advantage." (PMID 17375037, 2007). "According to a recent study, the combination of the androgen receptor antagonist enzalutamide and the ferroptosis-inducing substances erastin or RSL3 has an inhibitory effect on prostate tumor growth in vivo." (PMID 39869598, 2025). "Given that prostate tumor growth is driven by androgens and androgen receptors (AR), standard clinical treatment involves androgen deprivation therapy (ADT) combined with androgen receptor inhibitors, often supplemented with radiotherapy or chemotherapy." (PMID 40178629, 2025). "The prostate tumors that develop in mice with homozygous and +/− PTEN deletion are AR+ adenocarcinomas that, in most castrated mice, progress to mCRPC." (PMID 40227796, 2025). "By preventing MYLIP from tagging AR for lysosomal or proteasomal degradation, CNPY2 enhances AR stability and sustains downstream transcriptional programs essential for prostate tumor growth." (PMID 40001982, 2025). "Simulated AR inhibition resulted in significant differences in the changes in AUC of nodes involved in the TGF-β, IDH1, AR, and cell cycle pathways in prostate tumors between AA and EA men." (PMID 38566104, 2024).
prostate tumors (continued). "When the growth of prostate tumors is inhibited, the expression level of PSMA and androgen receptor decreases." (PMID 38637848, 2024). "Protein expression of AR and its target gene prostate‐specific antigen (PSA) was elevated in prostate tumors from PCa patients with metastasis as compared to patient with organ‐confined tumors." (PMID 39149855, 2024). "AR and NSD2 transcriptional activities were also positively correlated in primary prostate tumors from the TCGA cohort (R = 0.68, P = 2.2 × 10−16)." (PMID 39251788, 2024). "All metastases resembled primary prostate tumors and showed high levels of CK8 and SYP coexpression along with nearly undetectable expression of nuclear AR." (PMID 36928314, 2023). "High-grade prostate tumors exhibit low PSA expression, and AR therapy-resistant cells survive and develop castration-resistant cancer." (PMID 37282627, 2023). "We assessed the interaction between AR and phosphorylated MED1 in clinical prostate tumor specimens (57 cases) using proximity ligation assays (PLA), and revealed that it occurred in CRPC specimens, and not in benign prostate tissues or muscles." (PMID 36535377, 2023). "Only a low content of AR seems to be required to induce EMT phenotype as an inverse correlation between expression levels of AR and androgen-mediated EMT in prostate tumor epithelial cells has been demonstrated." (PMID 36009534, 2022). "Although the promotional role of androgen-signaling in prostate tumorigenesis has been implicated for many decades, the fundamental mechanisms by which the AR induces oncogenic transformation and initiates PIN and prostate tumor development are still unclear." (PMID 35902588, 2022). "MYC overexpression, which is observed in primary prostate tumors as well, has a profound role in the progression to a CRPC disease stage by counterbalancing the transcriptional activity of the AR and driving resistance to ARSI." (PMID 36212399, 2022). "In a cohort of 177 laser-capture microdissected foci of prostate tumors, KMT2A expression was positively correlated with MYC activity, AR activity, and HOXB13 expression, but decreased with tumor grade severity." (PMID 36181613, 2022). "At 35 weeks, IHC analysis showed AR+ prostate tumors in all mice, but expressions of Ki67+, c-MYC, p-IKKα/β, and p-p65 were lower in Tubb4a-cKO TRAMP versus WT TRAMP prostate tumors." (PMID 35589707, 2022). "Comparison between healthy tissue, primary prostate tumor and CRPC shows the AR cistrome to vary significantly." (PMID 35682963, 2022). "Inhibition of HSP70 significantly inhibits prostate tumor growth and improves anti androgen therapy in CRPC via AR/AR-V7 inhibition." (PMID 36294924, 2022). "In summary, our analysis of MYC-expressing prostate tumors demonstrates an inverse relationship with MEIS1 expression, which in turn is negatively correlated with HOXB13 expression and AR activity." (PMID 32681068, 2020). "Similar to observations of AR and IGF-1 expression, levels of the anti-apoptotic protein BCL-2 and the ratio of BCL-2/BAX, a marker of prostate tumor proliferative potential, were higher in animals submitted to the CS protocol than in all other groups." (PMID 32321149, 2020). "Elevation of AR expression and AR signaling promotes Pca metastasis by induction of EMT in prostate tumors." (PMID 32972001, 2020). "The membrane-bound AR (mAR) can trigger cytoskeletal reorganizations via FAK/Cdc24/Rac1/PI3K and modulate the adhesive and migratory activity of prostate tumor cells." (PMID 31877956, 2019). "Triple therapy with an AR inhibitor and two PI3K inhibitors resulted in near complete suppression of AR-dependent prostate tumors in vivo." (PMID 31366128, 2019). "Since MLL1‐fusion proteins are highly altered in NEPC and many of the fusion partners had interactions with the androgen‐receptor signaling pathway, we next set out comprehensively to explore MLL1 fusions in prostate tumors." (PMID 30548174, 2019).
prostate tumors (continued). "We analyzed TCGA gene expression profiles of 497 prostate tumor samples according to 43 genes involved in EMT and 3 hormone receptor genes (AR, ESR1, ESR2) as well as clinical characteristic of cancer patients." (PMID 29206234, 2017). "For example, MDM2 was shown to promote AR protein degradation, and thus MDM2 expression is predicted to attenuate AR-dependent transcription in prostate tumor cells." (PMID 27365400, 2016). "P300 acetylates AR at lysines KLKK633 and is critical for AR activation, lncoRNA binding, and prostate tumor development." (PMID 27659526, 2016). "Collectively, these results show that COPI coatomers modulate the expression of AR and PSA in prostate tumor cells." (PMID 27365400, 2016). "Thus, a molecular model of ligand-mediated AR activation, which is based upon direct interactions between AR and the AR-interactome as well as indirect interactions between proteins that bind to the AR-interactome in a spatial and temporal context, has yet to be validated in prostate tumor cells." (PMID 27365400, 2016). "Physical and functional interactions were detected between AR and CXCR7 in cells to demonstrate the biochemical integration of androgen signaling and cellular motility machinery at the molecular level in LNCaP prostate tumor cells." (PMID 25884570, 2015). "Tumors with overexpressed miR-190a had reduced expression of AR, YB-1 and Ki-67, and increased CDKN1A, suggesting that overexpression of miR-190a inhibited prostate tumor growth in vivo." (PMID 26314494, 2015). "On the other hand, in a mast cell-infiltrated prostate tumor region, the HOTAIR-polycomb repressive complex supresses AR transcription, consequentely promoting cell invasion with increased matrix metalloproteinase-9 (MMP9) expression." (PMID 26690121, 2015). "Increase in AR mRNA and protein was observed in CRPC tumors compared to the primary prostate tumors." (PMID 25788262, 2015). "SPDEF was originally discovered as a transcription factor that directly interacts with androgen receptor and functions as its co-activator to induce expression of prostate specific antigen (PSA) in LNCaP prostate tumor cells." (PMID 25254494, 2014). "PDEF was originally described as an mRNA transcript highly expressed in prostate tumor cells where it regulates PSA expression, acting as an AR co-regulator." (PMID 24681825, 2014). "To investigate the relationship between HSP90 inhibition and ARV expression in a more biologically relevant system, we evaluated AR and ARV expression in human prostate tumors cultured ex vivo in medium containing AUY922." (PMID 23674566, 2013). "FGFBP1 is secreted from AR+ PC3 cells in response to androgen, and is highly expressed in some human prostate tumor cells and the proliferation of these cells was dependent on these high expression levels." (PMID 20027305, 2009). "In summary, this work reveals that the AR- and ERα-dependent PI3K pathways are active in LNCaP and PC-3 human prostate tumour cells." (PMID 17486135, 2007). "Second, DU145 cells are derived from metastatic prostate tumors in the brain and are AR-negative, so that they probably only represent a small portion of metastatic CRPC such as DNPC subtype." (PMID 40995571, 2025). "Due to its ability to interfere with hormone receptors, particularly the androgen receptor (AR), a target for prostate tumors, which are classified as either AR positive or negative, rosemary has a noteworthy relation with PCa." (PMID 40429793, 2025). "We next investigated whether separate populations of AR activity–high and HER2-high cells coexist within the same prostate tumors, similar to what we have observed in vitro." (PMID 40906535, 2025). "These GSVA scores indicated AR transcriptional activity is significantly higher in prostate tumors than in adjacent non-tumor tissues (P < 0.05)." (PMID 38566104, 2024).
prostate tumors (continued). "We demonstrated in in vitro and animal models that Arc is a potent inhibitor of prostate tumor growth in non-obese and obese cases, partly through its inhibition of the AR and PI3K/Akt pathways." (PMID 38254705, 2024). "ITGB6 encoded the β6 integrin subunit, with significantly higher expression observed in metastatic castrate-resistant androgen receptor-negative prostate tumors compared to androgen receptor-positive tumors." (PMID 38877472, 2024). "Moreover, depletion of circRBM33 significantly increased the response sensitivity to androgen receptor signalling inhibitor (ARSI) therapy, including enzalutamide and darolutamide, in prostate tumours." (PMID 37056926, 2023). "The cellular heterogeneity of prostate tumors progressing from AR-positive adenocarcinoma to AR negative NEPC allows stratification of this disease into various subtypes." (PMID 36711033, 2023). "Interestingly, the positive correlation between AR and PARP7 expression appears to be lost in metastatic prostate tumors, suggesting that PARP7 becomes highly dependent on AHR signaling for its expression in advanced disease." (PMID 37077937, 2023). "The most common therapy is based on enzyme inhibitor treatments and AR antagonists, one of which is an inhibitor of a P450 enzyme (CYP17) converting precursors into steroids, leading to the deprivation of locally produced androgen in prostatic tumors." (PMID 37025180, 2023). "Collectively, these data support a cytoprotective role of autophagy in response to bicalutamide treatment in AR-dependent prostate tumor cells as AR-devoid cell lines did not demonstrate an autophagic response." (PMID 37894395, 2023). "In the present study, orthotopic prostate tumors stained positive for AR, PSA, and P504S and were p63 negative." (PMID 35168543, 2022). "As JAG1 and JICD expression levels are upregulated in 98% of prostate tumors, we investigated whether JAG1 regulated AR expression." (PMID 36428807, 2022). "Here, we report that transcript levels of ITGB6 (encoding the β6 integrin subunit) are significantly increased in metastatic castrate-resistant androgen receptor-negative prostate tumors compared to androgen receptor-positive prostate tumors." (PMID 35188070, 2022). "To explore the clinical relevance of stromal AR action as a tumor niche, we compared GSEA based on DEGs of basal versus luminal cell in human prostate tumors with those in our mouse models, and identified similar enriched signaling pathways between human samples and HiMyc mice." (PMID 36323713, 2022). "As TR3 and AR expression levels are positively correlated in prostate tumors, we investigated whether TR3 regulates AR expression." (PMID 35454821, 2022). "Immunohistochemical stains of the primary prostate tumor demonstrated positive staining of the AR, NKX3.1, and PSMA, and negative staining for neuroendocrine (NE) markers synaptophysin, chromogranin A, and DLL3." (PMID 34385567, 2021). "A study found prostate tumours that had a mean AR gene copy number of 2.7-28 per cell, as opposed to the intended one copy dramatically increased AR protein level." (PMID 33993099, 2021). "The report says genistein blocks the proliferation and multiplication of estrogen and androgen receptor-positive and negative mammary and prostate tumor cells in vitro." (PMID 34573087, 2021). "The current clinical ARPIs, such as enzalutamide, do not target the entire repertoire of genes regulated by the AR in prostate tumour cells." (PMID 34382934, 2021). "Recently, we have shown that myeloid AR does not affect myeloid cell infiltration into subcutaneously implanted C2 prostate tumors, suggesting that AR does not affect blood monocytes tumor migration." (PMID 33193298, 2020). "Studies have shown HOXB13-mediated repression of Androgen Receptor (AR) signaling, suggesting that HOXB13 may function as a growth suppressor in prostate tumors." (PMID 32012197, 2020).
prostate tumors (continued). "We previously found that arctigenin is a strong inhibitor of the AR signaling in non-obese state both in vitro and in vivo, while it is a stimulator of the Nkx3.1 signaling in prostate tumor cells." (PMID 31996731, 2020). "When compared to advanced but localized prostate tumors in B6 Hi-Myc mice, B6CaP allografts maintained a similar phenotype of luminal cytokeratin expression (CK8), strong androgen receptor (AR) expression, and high levels of MYC expression from the Hi-Myc transgene." (PMID 31839878, 2019). "Thus, known AR-regulated genes are differentially expressed in ETS− prostate tumors compared to ETS+ tumors, suggesting AR activates distinct biological pathways in ETS− versus ETS+ PCa." (PMID 30367117, 2019). "AR, FOXA1, and GRHL2 (a co-regulator of AR) are key TFs that promote prostate tumor progression." (PMID 31515496, 2019). "Specifically, we found a statistically significant positive correlation (r) between GREB1 RNA level and AR output score across the primary prostate tumors from the TCGA dataset, but not GHRHR or KLF8." (PMID 30644358, 2019). "The advent and earlier use of effective AR-targeting agents has led to the increased appearance of resistance mechanisms where prostate tumor cells acquire novel neuroendocrine features and become independent of the AR signaling axis." (PMID 31200487, 2019). "Immunohistochemical analysis of prostate tumors of TRAP rats showed that the localization of AR and SV40 T expression was not altered in C21-treated animals, but did reveal a significant dose-dependent decrease in AR expression in both the VP and LP." (PMID 29568400, 2018). "ARCC-4 inhibits prostate tumor cell proliferation, degrades clinically relevant androgen receptor point mutants and unlike enzalutamide, retains antiproliferative effect in a high androgen environment." (PMID 30271980, 2018). "First, in our initial assessment of pathology slides of prostate tumors that were immuno-stained for DDB2, NRIP, and AR, we already found that some cribriform tumors had distinct expression patterns for these 3 proteins and thus we decided to clarify it using complete statistical analysis." (PMID 28212551, 2017). "AR positive stroma is also capable of inducing prostate tumour formation from grafted AR negative benign prostatic hyperplasia (BPH)-1 cells, but is hindered in mice which lack stromal AR in comparison to stromal AR positive mice." (PMID 28117763, 2017). "In PCa, signs of hypoxia and metabolic stress in the prostate tumour tissue are exacerbated following ADT, however, it has been suggested that this hypoxic microenvironment can, in fact, enhance the transcriptional activity of the androgen receptor (AR)." (PMID 28410543, 2017). "Extensive biochemical and molecular experiments showed that the COPI retrograde complex regulates ligand-mediated AR transcriptional activation, which correlated with the mobilization of the Golgi-localized ARA160 coactivator to the nuclear compartment of prostate tumor cells." (PMID 27365400, 2016). "Overall, these results show that the effects of COPI coatomer knockdown on AR-dependent transcription are independent of the UPR pathway in LNCaP prostate tumor cells." (PMID 27365400, 2016). "This notion is further exemplified by the fact that CSCs isolated from human prostate tumors express basal markers (such as p63), but not the AR or markers of luminal differentiation, mirroring the phenotype of normal prostate stem cells." (PMID 26880966, 2016). "Aberrant AR signaling pathways promote prostate tumorigenesis, and because COPI coatomers modulated AR transcriptional activity in prostate tumor cells, we wanted to determine COPI coatomer expression across normal prostate tissue, localized prostate cancers, and metastatic prostate cancers." (PMID 27365400, 2016). "The reduction of NAIP was not seen in AR− PC-3 prostate tumors, further confirming that immunogenic modulation by enzalutamide is strictly dependent upon AR expression." (PMID 25344864, 2014).